SIRT1 (sirtuin 1)
Diseases named in the same sentence as SIRT1 in open-access papers (continued):
Sharing a sentence is not in itself a finding about the gene and the disease.
psoriasis (continued). "We randomized 40 patients with moderate-to-severe psoriasis (4:1) to three escalating doses of SRT2104, a selective activator of SIRT1, or placebo." (PMID 26556603, 2015). "In our study, we demonstrated that NMN could ameliorate psoriasis-like symptoms and inflammation in an IMQ-stimulated mouse model and improve therapeutic prognoses by activating the SIRT1 pathway." (PMID 38397784, 2024). "Activation of SIRT1 counteracts oxidative-stress-induced damage and restores redox balance by inhibiting the MAPK, NF-κB and STAT3 pathways, thereby alleviating the course of psoriasis." (PMID 37445960, 2023). "The mRNA expression of STAT3 was up-regulated while SIRT1 was down-regulated in human psoriasis skin tissues than normal skin tissues via RT-PCR detection." (PMID 34044769, 2021). "Furthermore, cigarette smoke has been shown to suppress SIRT1 activity, contributing to chronic inflammation in psoriasis patients who already exhibit negative alterations in SIRT1 expression." (PMID 35847770, 2022). "In particular, evidence for the role of SIRT1 in restoring redox balance in psoriasis was obtained from an in vitro study of psoriatic fibroblasts in which the levels of 8-iso-PGF2α and intracellular ROS were significantly reduced after the addition of SRT1720, a selective activator of SIRT1." (PMID 35883760, 2022). "In addition, through the SIRT1-dependent pathway, the inhibition of p-STAT3 and a-STAT3 expression by glycyrrhizin may also be related to the improvement of psoriasis." (PMID 34044769, 2021). "Together, these results indicated that glycyrrhizin improved psoriasis by inhibiting the expression of IL-17A and IFN-γ in vivo and suppressed the proliferation of IL-17A-HaCaT cells and the expression of STAT3, p-STAT3, and a-STAT3 by upregulating SIRT1 in vitro." (PMID 34044769, 2021). "The activation of SIRT1 could effectively inhibit MAPK, NF-κB, and STAT3 phosphorylation, thereby decreasing the expression of downstream genes and secretion of inflammatory cytokines, eventually blocking the development of psoriasis." (PMID 31495284, 2019). "In addition, levels of sirtuin 1 (SIRT1), a NAD+-dependent protein deacetylase that removes acetyl groups from various proteins and also acts as a transcription factor, may be important in psoriasis." (PMID 35883760, 2022). "In this study, we found that glycyrrhizin can attenuate the promotion of a-STAT3 induced by SIRT1, which suggests that glycyrrhizin may attenuate the response of keratinocytes to IL-22 by inhibiting the expression of a-STAT3, thereby playing a role in improving psoriasis." (PMID 34044769, 2021). "SIRT1 could counteract the activation of NF-kB pathways or MAPK proinflammatory pathways by its deacetylases activities, thus maintaining or activation of SIRT1 expression can effectively resolve various inflammatory diseases, especially in the psoriasis-like symptoms." (PMID 33323018, 2021).
breast tumors (21 papers, 2006 to 2025). "SIRT1 shows a significant role in the development and metastasis of breast tumours, but its underlying mechanisms are still poorly understood." (PMID 36505828, 2022). "They showed that SIRT1 deficiency downregulates ER-α-mediated estrogen response genes in vivo, impairing ER-α-mediated signaling pathways in breast tumors." (PMID 30380732, 2018). "Another study confirmed this finding at the gene level, as patients with ER+ PR+ Her2- breast tumors had a higher genetic expression of SIRT1 compared to TNBC." (PMID 39858444, 2025). "Explicitly, genomic profiling of these epigenetic enzymes displayed increases in HDAC1, 2, 8, 10, 11, and Sirtuins (SIRTs) 6 and 7, and decreases in HDAC4-7, -9, and SIRT1-4 levels, respectively, in TCGA breast tumors." (PMID 38003678, 2023). "SIRT1 interferes with various signalling pathways that promote breast tumour cell proliferation, migration, and invasion." (PMID 36505828, 2022). "Several studies have found that SIRT-1 is upregulated in breast tumor tissues and acts as an oncogene." (PMID 34986886, 2022). "On the other hand, alternative studies reported an oncogenic role of SIRT1 in luminal breast tumors." (PMID 30380732, 2018). "They showed that ER-α physically binds to and functionally cooperates with SIRT1 toward the stimulation of breast tumor cells." (PMID 30380732, 2018). "Recent studies suggest that psammaplins induce Sirtuin 1-dependent autophagic cell death in human breast tumor cell lines and xenografts." (PMID 30423844, 2018). "These novel findings suggest that SIRT1 plays a dual role in breast tumors depending on its expression rate and the molecular subtype of the cancer." (PMID 29340027, 2017). "Together, these results indicate that MSCs-Sirt1 can suppress breast tumor growth through proliferation inhibition and apoptosis induction." (PMID 27782173, 2016). "Overall, our results suggest that MSCs-Sirt1 can effectively inhibit breast tumor growth via the recruitment of NK cells in tumor inflammatory microenvironment." (PMID 27782173, 2016). "Biologically, we show that GPER and SIRT1 contribute to the growth effects triggered by E2 and G-1 in vitro, as well as in breast tumor xenografts." (PMID 26225773, 2015). "Noteworthy, SIRT1 contributes to tumor growth elicited by ligand-activated GPER as assessed both in vitro as well as in breast tumor xenografts." (PMID 26225773, 2015). "SIRT1 deacetylates several histones and plays a role in tumorigenesis and expression levels were increased in breast tumors compared to their matched normal breast tissues." (PMID 25139823, 2014). "Finally, fatty acid metabolic remodeling by adiponectin and the key role of SIRT-1 were confirmed in nude mice bearing breast tumor xenografts." (PMID 34986886, 2022). "Our data illustrate that SIRT4 negatively regulates SIRT1 expression in breast tumors." (PMID 32863939, 2020). "The authors noticed that lack of BRCA1 in BRCA1-mutant breast tumors is associated with reduced expression of SIRT1 and high levels of survivin, and showed BRCA1 to positively regulate SIRT1 expression in vitro." (PMID 30380732, 2018). "Since an abundance of SIRT1 expression is observed in breast tumors, many studies assert an oncogenic role of SIRT1 in breast carcinogenesis, and clinical studies demonstrated SIRT1 as a prognostic factor that significantly correlates with unfavorable clinicopathological factors." (PMID 30380732, 2018). "The post-hoc analysis distinguished 3 distinct patterns of SIRT1 enrichment depending on human breast tumors subtypes, SIRT1 was found to be most enriched on target gene promoters in luminal B subtypes, then luminal A and HER2-enriched subtypes and finally, least enriched in TNBC subtype." (PMID 30093977, 2018). "Thus, the data support KLF4 as a key CSC-related transcription factor, reversely regulated by SIRT1 in breast tumors." (PMID 30038266, 2018).
breast tumors (continued). "Additionally, the direct interaction between SIRT1 and both epi-marks is significantly increased in breast tumors compared to matched normal tissues." (PMID 30093977, 2018). "Also, there are very few reports available where expression of SIRT1 is comprehensively analyzed in breast tumors classified by molecular subtype." (PMID 29340027, 2017). "In order to determine whether SIRT1 transcription levels are equally translated into functional proteins, SIRT1 protein levels were assessed in breast tumors and their matched normal tissue samples using immunoblot analysis." (PMID 29340027, 2017). "Firstly, we found that MSCs could accelerate breast tumor growth with promoted proliferation and inhibited apoptosis, whereas MSCs-Sirt1 significantly suppressed tumor growth with proliferation inhibition and apoptosis promotion." (PMID 27782173, 2016). "Therefore, we designed the current study to investigate the effect changes of MSCs on breast tumor growth after they were infected with the Sirt1 overexpression." (PMID 27782173, 2016). "Survival analyses of OS and RFS showed that the combined expression level of LSD1, HDAC2 and SIRT1 in breast tumors was more predictive for patient survival and tumor relapse than each of the individual markers separately in both univariate and multivariate analyses." (PMID 25139823, 2014). "For chemoresistance, the interaction of CD44 with p300 and SIRT1 is found to regulate β-catenin signaling and NFκB-specific transcription activity, leading to MDR1 and Bcl-xL gene expression and chemoresistance in breast tumor." (PMID 38542115, 2024). "Quantitative data confirmed a strong positive correlation between endogenous SIRT1 and PRRX1 levels in breast tumors (R = 0.867, P = 0.001)." (PMID 30038266, 2018). "We found that with the optimal two-gene classifier (SIRT1, CREBBP) about 80% of these independent breast tumour samples could be correctly classified." (PMID 16638127, 2006). "Furthermore, the inverse correlation between SIRT1 and the 3 epi-marks expression patterns in transfected versus non-transfected cell lines is similar to that found in breast tumors compared to matched normal tissues." (PMID 30093977, 2018).
chronic myeloid leukemia (21 papers, 2012 to 2025). "Indeed, it is known that sirtuin 1 is responsible for acquisition of genetic mutations in BCR-ABL in chronic myelogenous leukemia cells, conferring resistance to imatinib mesylate, which inhibits that tyrosine kinase." (PMID 24127549, 2013). "Previous studies have shown that SIRT1 promotes acquisition of genetic mutations for drug resistance and leukemogenesis in CML (chronic myeloid leukemia)." (PMID 26646449, 2016). "Interestingly, recent studies revealed that in chronic myelogenous leukemia (CML) SIRT1 inhibition can prevent the acquisition of mutations and may therefore represent a treatment to overcome drug resistance." (PMID 23045412, 2012). "Combination treatment with 17-AAG and a SIRT1 inhibitor successfully targeted CSCs that are resistant to current therapies in CD44high chronic myeloid leukemia." (PMID 37474578, 2023). "To assess this, we used HAP1 cells, a near-haploid cell line derived from KBM-7 chronic myeloid leukaemia cells, where either SIRT1, 3 or 6 had been deleted by CRISPR-Cas9 mutagenesis." (PMID 34750509, 2021). "Our results suggest that interfering with Sirt1 leads to a partial restoration of BMAL1 oscillation in chronic myeloid leukemia patient samples." (PMID 30210557, 2017). "Tenovin‐6 (a small‐molecule inhibitor of SIRT1 and SIRT2) treatment yielded a significant loss of imatinib‐resistant chronic myeloid leukemia (CML) CD34+ stem cells in vivo." (PMID 28994177, 2017). "SIRT1 is an interesting druggable target to halt tumor cell proliferation with successes in chronic myeloid leukemia and with an inhibitor found to be safe in a clinical trial." (PMID 27494892, 2016). "Recently, SIRT1 has been demonstrated to promote Bcr-Abl-driven leukemogenesis and the survival of chronic myelogenous leukemia stem cells." (PMID 25884180, 2015). "SIRT1 inhibition induces elimination of CSCs in chronic myeloid leukemia." (PMID 27926488, 2017). "Class III HDAC SIRT1 controls CSCs in chronic myeloid leukemia." (PMID 27926488, 2017). "Moreover, SIRT1 downregulation by RNAi promoted etoposide-induced DNA damage in chronic myeloid leukemia cells accompanied with reduced NHEJ activity, but increased Ku70 acetylation." (PMID 26646449, 2016). "Of note, SIRT1 has been demonstrated to promote the development of chronic myelogenous leukemia." (PMID 25884180, 2015).
optic neuritis (20 papers, 2012 to 2024). Optic neuritis is inflammation of the optic nerve, the nerve that carries the visual signal from the eye to the brain.The conditionmay cause sudden, reduced vision in the affected eye(s). "It is known that intravitreal injection of SIRT1 agonists inhibits the loss of RGCs in a dose-dependent manner by inducing SIRT1 activity in mice with optic neuritis." (PMID 36949521, 2023). "SIRT1 has been shown to be associated with ocular diseases such as cataract, retinal degeneration, optic neuritis, and uveitis." (PMID 31287252, 2019). "In the present study, we interrogated the effects of SIRT1 or NRF2 overexpression in experimental optic neuritis via adeno-associated virus (AAV) gene transfer to RGCs." (PMID 29494741, 2018). "Intravitreal injection of SIRT1 agonists inhibits RGC loss in a dose-dependent manner by inducing SIRT1 activity in mice with optic neuritis." (PMID 28197299, 2017). "In vivo, SIRT1 activators prevent RGC loss during EAE optic neuritis, but specific increase in SIRT1 activity in optic nerve was not assessed." (PMID 24383546, 2014). "We previously showed three distinct SIRT1 activators attenuate RGC loss induced by experimental optic neuritis." (PMID 23293585, 2012). "Previous studies showed SIRT1 activators significantly attenuate RGC loss in experimental optic neuritis, although molecular mechanisms of effects on neuronal survival are not well understood." (PMID 23293585, 2012). "In experimental optic neuritis, small-molecule activators of SIRT1, including resveratrol and related polyphenolic compounds, effectively preserve visual acuity and retinal ganglion cells (RGC) survival in EAE and virus-related demyelinating diseases." (PMID 36949521, 2023). "Other investigators examined the potential neuroprotective effects of SRT647 and SRT501, two structurally and mechanistically distinct activators of SIRT1, an enzyme involved in cellular stress resistance and survival in optic neuritis." (PMID 36949521, 2023). "Neuroprotection by SIRT1 activators has been reported in optic neuritis models simulated in a neurotropic strain of mouse hepatitis virus, MHV-A59." (PMID 35740955, 2022). "In another study, SIRT1 activation attenuated optic neuritis induced by a neurotropic strain of hepatitis virus and MHV-A59 and reduced ROS levels." (PMID 34887866, 2021). "Both nuclear factor (erythroid-derived 2)-like 2 (NRF2) and sirtuin 1 (SIRT1) can protect and prevent RGC loss in experimental autoimmune encephalomyelitis (EAE) induced optic neuritis." (PMID 33920974, 2021). "The present study explored the effects of SIRT1 or NRF2 gene transfer in experimental optic neuritis." (PMID 29494741, 2018). "Collectively, this study demonstrates at least partial neuroprotective effects of NRF2 and SIRT1 gene augmentation in the context of experimental optic neuritis, and suggests an important role of these signals in MS pathogenesis." (PMID 29494741, 2018). "To date, only a few studies reported the role of SIRT1 with the development of cataract, retinal degeneration, optic neuritis, and uveitis." (PMID 28197299, 2017). "Oral treatment with the SIRT1 activating compound SRTAW04 significantly increased SIRT1 activity within optic nerves and prevented neuronal loss during optic neuritis, an inflammatory demyelinating optic nerve lesion that occurs in MS and its animal models." (PMID 24383546, 2014). "Activation of SIRT1, an NAD+-dependent deacetylase, prevents retinal ganglion cell (RGC) loss in optic neuritis, an inflammatory demyelinating optic nerve disease." (PMID 23293585, 2012). "Results suggest SIRT1 activators can mediate neuroprotective effects during optic neuritis by these mechanisms, and they have the potential to preserve neurons in other neurodegenerative diseases that involve oxidative stress." (PMID 23293585, 2012).
optic neuritis (continued). "Even though SIRT1 exerts anti-inflammation-independent neuroprotective effects in our optic neuritis model, other studies reported that SIRT1 regulates genes and proteins involved not only in apoptosis and senescence but also inflammation pathways in different biological settings and tissues." (PMID 35740955, 2022). "tested whether activators of SIRT1, namely, SRT647 and SRT501, prevent neuronal loss caused by optic neuritis in an SJL/J model of experimental autoimmune encephalitis (EAE)." (PMID 34887866, 2021). "In optic neuritis, the SIRT1 pathway was shown to be activated in the setting of ST266 treatment and could be acting by increasing mitochondrial biogenesis via PGC1α." (PMID 33406093, 2021). "While we did observe evidence of neuroprotection upon RGC function and viability, overexpression of neither NRF2 nor SIRT1 was able to suppress the inflammatory and demyelinating phenotype associated with optic neuritis." (PMID 29494741, 2018). "Furthermore, the results suggest that SIRT1 activators may mediate neuroprotective effects during optic neuritis and potentially preserve neurons in other neurodegenerative diseases associated with oxidative stress." (PMID 36949521, 2023). "We previously showed that RSV and other SIRT1 activators reduce RGC loss in EAE models of optic neuritis, and therefore provide an important potential therapy to prevent the neuronal damage that leads to permanent neurologic disability in optic neuritis and MS patients." (PMID 23293585, 2012). "EAE mice were used to determine the effects of AAV7m8-mediated SIRT1 delivery on visual function and RGC survival during optic neuritis." (PMID 35740955, 2022). "With the AAV7m8.SNCG.SIRT1 tool in hand, we were able to perform a proof-of-concept study testing whether RGC-targeted, SIRT1 expression is a potential gene therapy for optic neuritis." (PMID 35740955, 2022). "The present study was undertaken to determine the effects of SIRT1 gain of function via a novel synthetic vector (AAV7m8) combined with an RGC-selective promoter (SNCG) on retina and optic nerve alterations and visual function in EAE-induced optic neuritis." (PMID 35740955, 2022). "For EAE optic neuritis studies specifically, it was not clear whether SIRT1 upregulation was needed directly in RGCs, or whether upregulation in other cells induced secondary effects leading to RGC survival." (PMID 35740955, 2022). "Interestingly, prior studies using other strategies to upregulate SIRT1 have had variable effects on demyelination in EAE optic neuritis unlike the significant reduction found here with RGC-selective gene delivery." (PMID 35740955, 2022). "Results are similar to prior studies using pharmacologic or non-cell-specific gene therapy methods to upregulate SIRT1, which consistently demonstrated RGC neuroprotection in optic neuritis without suppression of optic nerve inflammation." (PMID 35740955, 2022). "Of note, pharmacologic upregulation of SIRT1 has also consistently shown an ability to attenuate RGC loss without suppressing optic nerve inflammation in EAE, suggesting that inflammatory responses specifically in EAE optic neuritis may not be modulated by SIRT1." (PMID 35740955, 2022).